ERBB2 (erb-b2 receptor tyrosine kinase 2)
Diseases named in the same sentence as ERBB2 in open-access papers (continued):
Sharing a sentence is not in itself a finding about the gene and the disease.
breast cancer (continued). "HER-2-enriched tumors (ERBB2+) express high HER-2 levels but do not express ER or PR and accounts for approximately 5% of breast cancers with aggressive spreading behavior." (PMID 30335837, 2018). "Immunity gene expression did not appear to coincide with expression of basal cytokeratins or signals from HER2(ERBB2) and steroid receptors, implying that the expression of immunity genes was not correlated with breast cancer subtypes." (PMID 30393759, 2018). "Previous studies reported an association between APOBEC3B expression and aggressive characteristics of the primary breast cancer, including high histologic grade, genomic grade, advanced stage, negative ERα status and HER2/ERBB2 amplification." (PMID 28141868, 2017). "Hence, since selumetinib downregulates ErbB2 protein in detached breast cancer cells, whereas activated Mek upregulates ErbB2 protein in detached breast epithelial cells, the effect of Mek on ErbB2 protein in such cells does not involve changes in the ErbB2 mRNA." (PMID 29285258, 2017). "Key breast cancer prognostic markers, such as PGR (t test P = 0.168; fold change = 0.76) and ERBB2 (t test P = 0.123; fold change = 1.23), showed no change between the two patient categories." (PMID 28522855, 2017). "From three models of breast cancer studied by Bulavin and others Wip1 deletion attenuated mammary gland tumorigenesis only in MMTV -Erbb2 and MMTV-HRAS1 mice, but not in MMTV-WNT1 mice." (PMID 26883196, 2016). "On the other hand, we found that CCB consumption increased the odds of breast cancer in postmenopausal women, women with BMI over 25 kg/m2, cancer in stages III-IV, non-ductal cancer and Erbb2+ cancer." (PMID 27508297, 2016). "These authors did not detect amplification in the ERBB2 negative, as it happens in human ERRB2- breast cancer cases." (PMID 29056725, 2016). "Triple negative breast cancer (TNBC), defined as the absence of both hormone receptor expression and erb-B2 receptor tyrosine kinase 2 (ERBB2) overexpression, accounts for approximately 15-20 % of all breast cancers." (PMID 26907936, 2016). "These basal type breast cancer cells of MDA-MB-231 cells and SK-BR-3 cells are known as triple-negative breast cancers for ER, progesterone receptor and erbB2 with poor prognosis." (PMID 27144558, 2016). "About 30% of breast cancer patients express HRG, often in the absence of the ERBB2 amplicon of which many are both HER2 and ERα-positive (e.g. Luminal B subtype)." (PMID 27472465, 2016). "Other key features to note are that MDA-MB-361 and SKBr3 harbor ERBB2 amplification, MDA-MB-361 was isolated from a breast cancer-derived metastatic brain tumor, and SKBr3 cells do not express estrogen receptor (ER-negative)." (PMID 25668816, 2015). "Focusing on the isoform HRGβ2, our previous studies in mice have shown that HRGβ2 overexpression, independent of estrogen stimulation or high levels of the HER2 (erbB-2) oncogene, is sufficient for the generation of adenocarcinomas while favoring the metastatic spread of breast cancer(BC) cells." (PMID 26327598, 2015). "Even though EGFR is not a strong oncogene in breast cancer and the overexpression of EGFR cannot induce mouse mammary cancer by itself, it can co-operate with ErbB2 in MCF10A cells making them invasive in 3-dimensional Matrigel assays." (PMID 24709902, 2014). "To study the metabolic flexibility of breast cancer cells lacking LKB1, we treated ErbB2-positive tumor cells with the complex I inhibitor metformin and investigated its impact on ECAR." (PMID 24280377, 2013). "Chemical carcinogens are generally not, however, considered significant inhuman breast cancer etiology; therefore, in the current study, we investigated the roleof tumor cell COX-2-derived mediators in ErbB2 (HER-2/neu)-induced mammarytumorigenesis." (PMID 24004819, 2013).
breast cancer (continued). "The MDA-MB-231 cell line was selected as a ‘triple negative’ breast cancer cell line, which lacks expression of the estrogen receptor (ER) and the progesterone receptor (PR) and does not amplify or overexpress HER2/ErbB2." (PMID 23406016, 2013). "Two human breast carcinoma cell lines, MCF7 without expression of ErbB2 and BT474 overexpressing ErbB2, were employed to evaluate the role of EC1-GLuc-p53C in specific bioluminescence imaging and cancer therapy." (PMID 24069396, 2013). "In sum, the loss of HDAC1 and HDAC2 increases C3 and NCOA2, but not CLU, ERBB2, MYC, or PGR, providing evidence that C3 and NCOA2 are repressed in breast cancer cells by the HDAC1/2 components of the Sin3A repressive complex." (PMID 20920219, 2010). "Despite the fact that there are no mouse models of ERBB2 and ESR1 function in breast cancer, there is good potential for novel models to be generated for dissecting the roles of these two proteins." (PMID 19007432, 2008). "As a result of these advances, a breast cancer cluster with poor prognosis that is negative for the estrogen receptor (ESR1), the progesterone receptor (PRGR) and ERBB2 (triple negative) has come to the forefront of medical therapeutic attention." (PMID 19007432, 2008). "However, in breast cancer cell lines, regardless of whether the gene is amplified, there is a higher ERBB2 mRNA level per gene copy in overexpressing tumor cells compared with cells with a low ERBB2 expression." (PMID 18218085, 2008). "Rather than inhibit upstream ERBB2 signaling, the present approach was designed to inhibit downstream NFκB and AP-1 activation in the TAM-resistant breast cancer models." (PMID 17407600, 2007). "Furthermore, ERpHER2n-HER2E breast cancer does not consist of misclassified or HER2-low cases, has little impact of ERBB2, is highly proliferative and less ER dependent than other luminal subtypes." (PMID 40044693, 2025). "All MaPR245W/− mammary tumors were TNBC lacking Esr1, Pgr, or Erbb2 expression." (PMID 38994678, 2024). "Triple-negative breast cancer (TNBC), a breast cancer subtype characterized by lack of estrogen and progesterone receptor expression and absence of EGFR-2 (HER2/erbB2) overexpression, accounts for 15–20% of all breast cancers and most commonly affects young women under the age of 45." (PMID 38072918, 2023). "To build an ERBB2 mRNA expression assay that tracks with clinical HER2 status, we combined the Short-HER HER2-positive cohort (n=434) with a HER2-negative cohort of patients newly diagnosed of early-stage breast cancer at Hospital Clinic (n=203) (Figure." (PMID 34990895, 2022). "We noted that ESR1, ERBB2, PIK3CAGS might not work on the whole breast cancer cohort even though they have been found to be effective in specific breast cancer cohorts." (PMID 34082714, 2021). "In light of the role of hyperinsulinemia in breast cancer growth and migration, the robust insulin-sensitizing anti-diabetic activity of MEDICA may translate to improved treatment of ErbB2 breast cancer in both diabetic and non-diabetic patients." (PMID 32695336, 2020). "Among the recurrently amplified and deleted loci, we noted that canonical oncogenes, such as EGFR and HRAS, were recurrently amplified in CMTs; however, amplification of ERBB2 and MYC, which is common in human breast cancers, was not reflected in the GISTIC peaks of CMTs." (PMID 32680987, 2020). "Breast cancers are often classified by the presence or absence of three receptors: estrogen receptor (ESR1), progesterone receptor (PGR), and the HER2 epidermal growth factor receptor (ERBB2)." (PMID 31684899, 2019). "Several distinct molecular subtypes, each associated with different clinical outcomes, have been identified by array and RNA-seq studies, and include: Luminal A and B, ERBB2 overexpression (the gene for the HER2/Neu protein), and normal breast-like and basal-like breast cancers (BLBCs)." (PMID 30720718, 2019).
breast cancer (continued). "Among these types of breast cancer, ER−/HER2− breast cancer, also known as triple-negative breast cancer (TNBC), because of the lack of ERα, PR, and ERBB2 expression, is the most aggressive subtype with advanced histological grade and poor clinical outcome despite appropriate treatment." (PMID 31779659, 2019). "To confirm these results, we repeated these experiments in breast cancer cell lines MCF-7 and ZR-75-1 (estrogen receptor positive), and SKBr3 cells (estrogen receptor negative, ErbB2 over expressed) as these cell lines represent different subtypes of breast cancer." (PMID 27441659, 2016). "We have previously demonstrated that short term exposure to ethanol (12–48 hours) increased migration/invasion in breast cancer cells overexpressing ErbB2, but not in breast cancer cells with low expression of ErbB2, such as MCF7, BT20 and T47D breast cancer cells." (PMID 26655092, 2016). "This does not rule out a role for the ErbB2-IRS cooperation in antiestrogen resistance, but suggests that ErbB2 amplified human breast cancers may have sufficient ErbB2-induced regulation and signaling." (PMID 27765041, 2016). "Well-studied subtype-specific breast cancer oncogenesCDK4 and FOXA1 are not classified as essential in any of the top 12 screens, including HCC-1954,though this line does show a dependence on Her2/ERBB2 (BF = 9.21)." (PMID 24987113, 2014). "Therefore, when compared with other subtypes of breast cancer, TNBC has no response to endocrine or anti-ERBB2 therapies and systemic chemotherapy is the major treatment for those patients after metastasis." (PMID 24529079, 2014). "Interestingly, over-expression of miR-125a did not significantly repress the expression of ERBB2 or ERBB3, which were demonstrated to be critical for inhibiting the proliferation and metastasis of breast cancer." (PMID 22768249, 2012). "In the case of breast cancer, the DEAD box helicase, DDX5, was found to be amplified and often co-amplified along with ERBB2, and breast cancer cell lines with amplification of the DDX5 locus were considerably more sensitive to its knockdown than breast cancer cell lines lacking this amplification." (PMID 23116066, 2012). "For many years, breast cancers were classified by whether or not they express various receptors, namely the estrogen receptor (ER/EsR1), the progesterone receptor (PR/PGR) and ErbB2." (PMID 19317917, 2009). "In addition, a recent study has shown that anti-apoptotic effect of rat Muc 4 is independent of ErbB2/HER2 in A375 melanoma and MCF-7 breast cancer cells, whereas dependent on ErbB2 in JIMT-1 breast cancer cells." (PMID 19738614, 2009). "Overexpression of miR-125a and miR-125b decreased ERBB2 and ERBB3 mRNA and protein levels, inhibited phosphorylation of ERK1/2 and AKT, and inhibited the anchorage-independent growth of ERα-negative/ErbB2-overexpressing SKBR3 breast cancer cells." (PMID 19881910, 2009). "In modern practice, the course of treatment is dependent upon three subcategories of breast cancer that are defined by the presence or absence of specific molecular markers for estrogen or progesterone receptors and human epidermal growth factor 2 (ERBB2; formerly HER2)." (PMID 34842655, 2021). "Novel antibody-drug conjugates against HER2 are showing high activity in HER2-negative breast cancer (BC) with low HER2 expression (i.e., 1+ or 2+ and lack of ERBB2 amplification)." (PMID 33397968, 2021). "For example, since the oncogene ERBB2 (HER2) is amplified in subgroups of glioblastoma and, stomach, uterine, bladder, and lung cancers, responsiveness to HER2-targeted therapy may or may not be analogous to that of HER2-amplified breast cancer." (PMID 29050243, 2017).
breast cancer (continued). "Although we see dramatic inhibition of the proliferation on breast cancer cells following G7-18NATE peptide treatment, we have not been able to detect changes in phosphorylation of ERK or AKT, two known molecules that have a role in cell survival downstream of ErbB2." (PMID 17426702, 2007). "Among 3916 patients with MBC, 1215 (31.0%) had HR-positive/ERBB2 (formerly HER2)-negative cancer, 310 (7.9%) had ERBB2-positive/HR-positive cancer, 200 (5.1%) had ERBB2-positive/HR-negative cancer, 258 (6.6%) had TNBC, and the remaining 1933 patients (49.4%) had an unknown breast cancer subtype." (PMID 35960523, 2022). "Importantly, in a recent study, researchers found that in breast cancer cells with acquired letrozole resistance, the constitutive activation of the AKT/mTOR pathway could be blocked by PI3K and/or mTOR inhibitors, but not by EGFR/ErbB2 inhibitors." (PMID 25633049, 2015). "Notably, β1 overexpression was identified as an independent negative prognostic marker in ErbB2-positive breast cancer patients treated with trastuzumab, and β1-activated pathways such as PI3K/Akt or Erk circumvented the antiproliferative activity of trastuzumab in breast cancer cell lines." (PMID 25606594, 2014). "Interestingly, our preliminary analysis of clinical breast cancers shows that IKZF3 is overexpressed in a small subset of both HER2-positive as well as HER2-negative cancers, suggesting its expression may be elevated independent of ERBB2 amplification." (PMID 21247443, 2011).
triple-negative breast carcinoma (4,843 papers, 2008 to 2026). An invasive breast carcinoma which is negative for expression of estrogen receptor (ER), progesterone receptor (PR), and human epidermal growth factor receptor 2 (HER2). "Does ERBB2-low expression and its association with clinical outcomes vary by race and ethnicity among patients with triple-negative breast cancer (TNBC)?" (PMID 40498483, 2025). "It has been reported that an aberrant decline or loss of ATM was identified in ER/PR/ERBB2-triple-negative breast cancer." (PMID 38027164, 2023). "Despite that, quite recently the canonical ERBB2 isoform and an ERBB2 variant located in the nucleus were suggested to drive triple-negative breast cancer growth." (PMID 35406375, 2022). "This cohort study assesses whether ERBB2-low status and its association with pathologic complete response and overall survival differ by race and ethnicity among patients with triple-negative breast cancer." (PMID 40498483, 2025). "Tumours not expressing the oestrogen receptor (ER) or progesterone receptor (PR) and have no human epidermal growth factor receptor 2 (HER2; also referred to by its gene name ERBB2) amplification are classified as triple-negative breast cancer (TNBC)." (PMID 40136651, 2025). "In contrast, ERBB2-positive (1966 patients [23.0%]) and triple-negative breast cancer (TNBC; 9631 patients [23.0%]) subtypes were much less frequent among mILC cancers." (PMID 40293750, 2025). "An abnormally low level of ATM was discovered in epidermal growth factor receptor 2 (ErbB2)-triple-negative breast cancer, suggesting the possible regulatory relationship between ATM and ErbB2." (PMID 38027164, 2023). "Overall, our data unveil that the NRG1β/ERBB3/ERRB2 axis promotes cell growth in suspension of basal-like/triple-negative breast cancer cells and that this process is efficiently prevented by the administration of anti-ERBB2 agents, in particular, pertuzumab." (PMID 35406375, 2022). "The neutralization of the NRG1β/ERBB3/ERBB2 axis deserves further studies as a therapeutic strategy for basal-like/triple-negative breast cancers, which today have very limited treatment opportunities." (PMID 35406375, 2022). "Incidence rates of 4 molecular subtypes: hormone receptor (HR)–positive and ERBB2-negative, HR-positive and ERBB2-positive, HR-negative and ERBB2-positive, and triple-negative breast cancer (TNBC)." (PMID 33074325, 2020). "Patients with triple-negative breast cancer are insensitive to endocrine therapy and ERBB2-targeted antibody treatment." (PMID 32164337, 2020). "PIK3CA and AKT1 mutations were found to be particularly enriched in the luminal B/HER2− subtype, NF1, and ERBB2 mutations were enriched in the luminal B/HER2+ mutation, and PTEN mutations were enriched in triple-negative breast cancer." (PMID 33173047, 2020). "This leading deadly disease is generally divided into luminal A, luminal B, HER2/ErbB2-positive, and triple-negative breast cancer subtypes according to the expression status of estrogen receptor, progesterone receptor, and HER2/ErbB2." (PMID 30786890, 2019). "The association of high ERR1 levels with poor prognoses, particularly in ER-negative/ErbB2(+) and triple-negative breast cancer, has heightened interest in targeting ERR1 and its modulators pharmacologically in breast and other steroidogenic cancers." (PMID 28881568, 2017). "This therapeutic deficit is particularly relevant to the clinical manifestations of triple-negative breast cancers (TNBCs), which lack expression of hormone receptors (estrogen receptor-α and progesterone receptor), and of the ErbB2/HER2 amplicon." (PMID 26682263, 2015). "Surprisingly, triple negative breast cancers (TNBCs; which express low levels of ErbB2, progesterone and estrogen receptors) are the most broadly responsive to growth factors and HER2amp cancers (which overexpress ErbB2) the least." (PMID 24655548, 2014).